SOD2 (superoxide dismutase 2)
Diseases named in the same sentence as SOD2 in open-access papers (continued):
Sharing a sentence is not in itself a finding about the gene and the disease.
cancer (continued). "DON treatment also resulted in decreased expression of SOD2 and CAT, which normally function to remove harmful ROS, and may thereby lower the cellular threshold for tolerating ROS for these cancer cells." (PMID 28801576, 2017). "SOD2, CDC42/Rac1, and JNK/c-Jun are all known to be involved in cancer development and migration." (PMID 25402510, 2015). "SOD2 is also considered to function as a negative modulator of cellular apoptosis and as a prosurvival factor for cancer cells." (PMID 25478571, 2014). "miR-382 also target superoxide dismutase 2 (SOD2) to mediate TGF-β1-induced epithelial-mesenchymal transition (EMT), which results in the acquisition of cell invasion and drug resistance, and reversion to cancer stem cells." (PMID 24914051, 2014). "In addition, we present evidence for increased LDHA and SOD2 expression in SDHB-PHEOs/PGLs, proteins that have been proposed as promising therapeutic targets in other cancers." (PMID 22859959, 2012). "In addition, asparagine depletion did not consistently affect expression levels of SOD2 in a panel of cancer cell lines as well as B-ALL PDXs." (PMID 40131931, 2025). "However, as a tumor promoter, a recent study showed that SIRT3 could enhance ovarian cancer metastasis by rapidly up-regulating SOD2, which was a new piece of evidence of SIRT3’s role in promoting metastasis in cancer." (PMID 35832551, 2022). "Furthermore, after the blockade of PPARγ/SOD2 pathway, ATG4D was located in mitochondria to activate the process of mitophagy, contributing to the increase of mitochondrial ROS production, damage of MMP stabilization and promotion of cancer cell apoptosis." (PMID 35186942, 2021). "We demonstrated clearly, in our experimental model, a significant overexpression of SOD2, GST, CAT, and HO-1 in MPM cells towards HMC, thus confirming the increase in antioxidant defense mediated by Nrf2 and a consequent alteration of redox balance, so increasing the survival of cancer cells." (PMID 33799965, 2021). "In addition, two patients with high FIGO class and tumors with low SOD2 expression have survived without any cancer relapses." (PMID 30700285, 2019). "In addition to modifications of glycolytic metabolism, SOD2 signal transduction via AMPK inhibits apoptosis and increases drug resistance and colony formation in vitro in soft agar, all characteristics of late-stage cancers." (PMID 29478325, 2019). "However, the increased levels of SOD2 protein and nitrosylation (indicated by expression of the unsaturated hydroxyalkenal 4-HNE) suggesting oxidative stress, were significantly higher in cancer patients (C) compared with healthy elderly (HE)." (PMID 27454226, 2016). "Therefore, the observation that in the absence of SIRT3, the activity of SOD2 is abolished, is a likely reason for the elevated ROS levels in cancer cells." (PMID 24955214, 2014). "Another explanation is that several cancer cell types have higher levels of antioxidants, which could inhibit ROS toxicity; specifically, increased levels of superoxide dismutase (SOD-2) and thioredoxin reductase 2 (TRX-2) were observed in mitochondria from cancer tissue samples." (PMID 25478322, 2014). "In addition, SOD2 knockdown led to the down-regulation of MMP1 expression, in agreement with previous observations that SOD2-dependent production of H2O2 regulates expression of MMP family members (including MMP1) and contributes to cancer cell metastasis." (PMID 22408395, 2012). "The pathway by which SOD2 expression might contribute to cancer development is not clear, but some researchers have suggested that, as a pro-oxidant protein, it promotes the accumulation of hydrogen peroxide, which can further lead to activation of various oncogenic pathways." (PMID 29774090, 2018). "However, so far, no study has demonstrated a specific role of ubiquitinated SOD2 in cancer." (PMID 29099803, 2017).
cancer (continued). "Therefore, for carcinomas in which there is decreased SOD2 activity, regardless of the mechanism, treatment with 2ME2 or other agents resulting in oxidative bursts may represent a potential treatment option." (PMID 17895890, 2007). "We also detected no statistical differences between the SOD2 expression and TNM staging subgroups/pathomorphological subgroups Nevertheless, our results are consistent with the evidence for a role for SOD2 in cancer development." (PMID 37660159, 2023). "We found AFG1 did not promote SOD-2 expression and EMT in cancer cells, but enhanced TNF-α and SOD-2 expression in MΦ-THP-1 cells." (PMID 28801561, 2017). "As for Nrf2, our results demonstrated an overexpression of SOD2 and CAT proteins in MPM cells and not in the mesothelium, thus confirm also for this factor its strong involvement in MPM resistance against oxidative stress and its overexpression in cancer cells." (PMID 33799965, 2021).
infection (100 papers, 2008 to 2025). The state of being infected such as from the introduction of a foreign agent such as serum, vaccine, antigenic substance or organism. "Volcano plots revealed that the most highly upregulated genes in response to OC43 infection, such as SOD2, CD44, STAT1 and MX1, were inflammation-associated genes and antiviral ISGs." (PMID 40368896, 2025). "For example, in first infection monocytes upregulate Sod2, which encodes a mitochondrial protein required to safeguard inflammatory macrophages from the reactive oxygen species that they produce." (PMID 33752799, 2021). "The reduction of SOD2 may make neurons even more susceptible to oxidative stresses during immune responses to infection." (PMID 32466166, 2020). "Gene therapy through infection of SOD2 on vascular wall may ameliorate E2 deficiency-induced cardiovascular damage in postmenopausal women." (PMID 25462070, 2014). "Indeed, lowering the stringency of the microarray analysis allowed the identification of over 70 genes, including several genes known to be associated with the mammary gland response to infection, e.g. SOD2, IL1B, LTF, S100A8 and S100A12." (PMID 23324411, 2013). "Furthermore, we have recently shown that SOD2 protein expression level is a potential biomarker for the characterization of different stages of cervical neoplasia, which is etiologically linked with infection with high-risk HPV types." (PMID 25745358, 2015). "Consistently, SOD2 protein levels were higher in N2aC24 cells than in N2aC24L1-3 cells after IAV/WSN infection." (PMID 39194237, 2024). "The decrease in catalase and SOD2 in different brain regions after BoDV1 infection, particularly in Wt and TNFR2ko mice, very likely destabilizes intracellular redox homeostasis, leading to oxidative stress and mitochondrial damage and loss." (PMID 38339126, 2024). "In summary, H37Ra infection greatly increases SOD2 expression to eliminate excess ROS and promote the survival of H37Ra in THP-1 cells." (PMID 36819778, 2023). "The expression of CAMK2B, GPX3, and SOD2 in the infection + NAC group was lower than that in the infection group (p < 0.05)." (PMID 38149012, 2023). "Sod1, Sod2, Cat, and Nrf2 transcripts were elevated in the E8.5 infection group only, with Hmox1 expression being predicted only by infection but not by infection day." (PMID 35312688, 2022). "In a multivariate model testing influence of both status and day on these transcripts, holding day constant revealed a significant impact of infection was retained for Nrf2, Sod1, Sod2, Cat and Hmox1 (p ≤ 0.04)." (PMID 35312688, 2022). "Transcripts for Nrf2, Sod1, Sod2, and Cat in placentae from E8.5 infections (i.e., E16.5) were all significantly elevated relative to placentae from mice infected at E6.5 (i.e., E15.5; p ≤ 0.01)." (PMID 35312688, 2022). "Another study indicates that the expression of SOD2 protein is increased in bronchial epithelial cells from COPD donors following infection with rhinovirus." (PMID 35609226, 2022). "Conversely, infection with a SOD2-expressing lentivirus (Tf-D-HKC8/↑SOD2) completely reversed this effect, whereas infection with an OGG1-expressing lentivirus (Tf-D-HKC8/↑OGG1) had little effect, compared with the control group (Tf-D-Scram/CTL)." (PMID 33423158, 2021). "Conversely, infection with a SOD2-expressing lentivirus (shHKDC1/↑SOD2) completely reversed this effect, whereas an OGG1-expressing lentivirus (shHKDC1/↑OGG1) had little effect, compared with the control group (CTL/EMP)." (PMID 33423158, 2021). "Only the WT RML-infected mice showed a change in their SOD2 expression as a result of infection, with a significant ~2-fold increase over NBH mice, although the ME7-infected WT mice also showed highly variable SOD2 levels." (PMID 34735539, 2021). "Recently, it was shown that the GPI-anchored Sod2 from the phytopathogenic fungus Puccinia striiformis suppressed ROS accumulation during infection and was essential for its virulence." (PMID 34356954, 2021).
infection (continued). "The variable SOD2 detection in our ME7 infections and the genotypes of this cohort were re-checked and a reason for the variability was not apparent." (PMID 34735539, 2021). "On the other hand, infection of SOD2 in HG(4d) + LG(4d)/↑SOD2 treatment completely restored this effect." (PMID 33633538, 2021). "At 7 days postinfection, the CFUs from infection with the sod2Δ strain remained significantly lower in all tissues tested, except the lung, whereas the SOD2-CuRE1/2mut mutant reached colonization levels similar to that of the WT and SOD2C strain." (PMID 33567338, 2021). "SOD2 also appears to be a critical regulator of the innate immune response; SOD2 knockout zebra fish embryos had a significantly increased bacterial load at 20-h post-infection compared with wild-type controls." (PMID 32008371, 2020). "With the evolution of the infection, only SOD2 continues to increase, resulting in enhanced H2O2 production, whereas other antioxidant enzymes, including those that are critical for neutralizing H2O2, are suppressed." (PMID 33381273, 2020). "Amplification curve analysis showed that BE2C cell SOD2 expression in infected cells was significantly lower at all infection time-points in comparison with untreated cells (Mann–Whitney test, p ≤ 0.05)." (PMID 32466166, 2020). "It showed that HIF1β binding ability was decreased to 36% by HG(4d)+LG(4d) treatment compared to LG(8d)) group, and this was completely restored by either infection of ERβ lentivirus (↑ERβ) or SOD2 lentivirus (↑SOD2), or ERβ agonist (DPN) treatment." (PMID 31396159, 2019). "Again, infection of either ERβ lentivirus (HG(4d)+LG(4d)/↑ERβ), or SOD2 lentivirus (HG(4d)+LG(4d)/↑SOD2), or treatment with 100μM ERβ agonist (HG(4d)+LG(4d)/↑DPN) on day 4 completely restored 3-NT generation to normal." (PMID 31396159, 2019). "The infection of ERβ lentivirus (↑ERβ) or ERβ agonist (DPN) treatment further increased SOD2 reporter activity to 156 and 135%, respectively." (PMID 31396159, 2019). "Infection of ERβ lentivirus (↑ERβ) on day 4 significantly increased expression of ERβ and SOD2, and the expression remained high throughout the next 4 days." (PMID 31396159, 2019). "It showed that ERβ binding ability decreased to 58% as a result of HG(4d)+LG(4d) treatment compared to the LG(8d)) group, and this was completely restored by either infection of ERβ lentivirus (↑ERβ) or SOD2 lentivirus (↑SOD2), or ERβ agonist (DPN) treatment." (PMID 31396159, 2019). "Infection with rhinovirus significantly induced protein levels of manganese-dependent superoxide dismutase (SOD2) and copper-zinc superoxide dismutase (SOD1) (p < 0.05)." (PMID 31849956, 2019). "On the other hand, either infection of SOD2 lentivirus (↑SOD2), or ERβ agonist (DPN) treatment significantly increased SOD2 expression, but did not increase ERβ expression." (PMID 31396159, 2019). "In response to S. pneumoniae, there was augmented SOD1 and SOD2 mRNA expression in aged macrophages at 2 hours post infection." (PMID 30700745, 2019). "At 1.5 h, the transcriptome of IECs showed the induction of nuclear factor, erythroid 2 like 2 (nfe2l2) together with superoxide dismutase (sod2); their RNA levels peaked at 3 h of infection." (PMID 30062089, 2018). "The ROS resulting from infection, trauma, and exposure to toxic substances are converted to hydrogen peroxide by SOD2." (PMID 30035652, 2018). "A slight but significant accumulation of SOD2 mRNA was detected for Vero cells after infection with all RV strains, which was comparable to the positive control H2O2." (PMID 30282907, 2018). "Enzymes related to detoxification, such as superoxide dismutases, SOD1 (PADG_07418) and SOD2 (PADG_01755) were also accumulated in P. brasiliensis yeast at 6 h post-infection." (PMID 28704618, 2017). "E the acetylcholine-induced relaxation was significantly decreased by OVX surgery compared to control (CTL) group, and this effect was restored by the E2 treatment, but partly restored by the SOD2 infection." (PMID 25462070, 2014).
infection (continued). "We exposed human lung epithelial cells to the MP12 strain of RVFV and first evaluated the levels of the two major enzymes involved in the maintenance of cellular oxidative homeostasis, SOD1 and SOD2 at multiple time points after infection." (PMID 21655261, 2011). "ETBF infection also promotes intestinal inflammation and colorectal carcinogenesis by downregulation of miR-149-3p expression and subsequent superoxide dismutase 2 (SOD2) overexpression." (PMID 39769073, 2024). "However, until now, there has been no comprehensive study analyzing changes in the numerical abundances of peroxisomes and mitochondria and their respective main antioxidant enzymes, catalase and SOD2, after BoDV1 infection." (PMID 38339126, 2024). "After BoDV1 infection, a strong decrease in mitochondrial (2.1–6.5-fold), SOD2 (2.7–9.1-fold), and catalase (2.7–10.3-fold) abundances, but a slight increase in peroxisomes (1.3–1.6-fold), were detected in Wt and TNFR2ko mice, whereas no changes occurred in TNFR1ko mice." (PMID 38339126, 2024). "Importantly, the Nrf2 inhibitor luteolin reduced H37Ra infection-induced increases in SOD2 expression." (PMID 36819778, 2023). "Additionally, induction of the cytosolic isoform of SOD2 contributes to the ability of C. neoformans to colonize specific niches within the host during infection." (PMID 33567338, 2021). "Functionally, anakinra and SOD2 protects mice from pulmonary oxidative inflammation and infection." (PMID 34207085, 2021). "The results showed that HIF1α transcriptional activity decreased to 53% as a result of HG(4d)+LG(4d) treatment compared to the LG(8d) group, and the infection of either ERβ lentivirus (↑ERβ) or SOD2 lentivirus (↑SOD2), or ERβ agonist DPN treatment, completely restored this effect." (PMID 31396159, 2019). "The results showed that VEGF reporter activity decreased to 56% as a result of HG(4d)+LG(4d) treatment, and the infection of either ERβ lentivirus (↑ERβ) or SOD2 lentivirus (↑SOD2), or ERβ agonist DPN, increased VEGF reporter activity to 139, 136, and 115%, respectively compared to the LG(8d) group." (PMID 31396159, 2019). "However, on A549 cells as compared to Vero cells, the Wb-12 strain induced a higher mRNA level of SOD2 and p21 than 03-03703 indicating a higher oxidative stress level upon Wb-12 infection as compared to 03-03703." (PMID 30282907, 2018). "Markers of oxidative stress triggered by the infection resulting in elevated ROS levels were matched by corresponding increases in the levels of antioxidant proteins, such as peroxiredoxin-1 (Prdx1), superoxide dismutase (Sod2), and glutathione S-transferase (Gstm3) in lung tissues." (PMID 36614003, 2022). "In EGFP-PrP23-51-transduced N2aC24 cells, p65 nuclear translocation was disturbed, SOD2 expression and phosphorylated MLKL were decreased, and cell viability was increased after IAV/WSN infection." (PMID 39194237, 2024). "In contrast, SN50 reduced p65 nuclear translocation, SOD2 expression, and phosphorylated MLKL in N2aC24 cells after IAV/WSN infection." (PMID 39194237, 2024). "Compared with the blank group, the mRNA levels of SOD1, SOD2, and SOD3 were significantly increased on the fifth day after PR8 infection." (PMID 36829913, 2023). "In vivo, whole body exposure to PM10 vs. control air exposed mouse corneas showed early perforation and/or corneal thinning at 3 days post infection, accompanied by increased TNF-α and decreased SOD2 protein levels." (PMID 37868351, 2023). "Overall data revealed alleviated levels of SOD2 gene and decreased expression of SOD1 gene in response to C. trachomatis-infection leading to production of oxidative stress and RSA." (PMID 36038649, 2022). "SOD1, SOD2, and Catalase expression were studied, finding SOD1 downregulation after 24 and 48 h of infection." (PMID 36358519, 2022).